E2F1 (E2F transcription factor 1)
Diseases named in the same sentence as E2F1 in open-access papers (continued):
Sharing a sentence is not in itself a finding about the gene and the disease.
colorectal cancer (72 papers, 2011 to 2026). A primary or metastatic malignant neoplasm that affects the colon or rectum. "Protein encoded by KDM5D seems to act on E2F1 through demethylation, thereby suppressing cell growth and metastasis in some form of colorectal cancer." (PMID 38279299, 2024). "Increased expression of E2F1 has been linked to decreased proliferation and increased apoptosis in colorectal cancer." (PMID 26465597, 2015). "In contrast, high expression of E2F1 promotes apoptosis in colorectal cancer, and is associated with a favorable prognosis; its high expression also induces insensitivity to treatment with 5-fluorouracil (5-FU) in colorectal cancer patients." (PMID 28797284, 2017). "E2F1 expression has been associated with poor prognosis in different types of cancers, such as in colorectal carcinoma (CRC) or breast cancer." (PMID 35326607, 2022). "KAT2A, a histone acetyltransferase, promotes cell proliferation and invasion by acetylating H3K9 and activating E2F1 in colorectal cancer." (PMID 40949882, 2025). "Several studies have indicated that E2F1, as a transcription factor, can promote the proliferation, migration, invasion, and metastasis of colorectal cancer by regulating its target genes." (PMID 41425852, 2025). "DSCC1's regulation involves various transcription factors; for instance, in colorectal cancer, the upregulated transcription factor E2F1 possesses binding sites within the DSCC1 promoter, resulting in DSCC1 upregulation and impacting colorectal cancer cells." (PMID 39309429, 2024). "DTX3 governs the growth of colorectal cancer cells by regulating E2F1 and the downstream genes CDC2 and cyclin D332." (PMID 38992083, 2024). "In bladder cancer and colorectal cancer, the transcription factor E2F1 was discovered as an oncogenic component." (PMID 35790898, 2022). "Consistently, overexpression of E2F1 observed in both osteosarcoma and colorectal cancer tissues were related to TNM stage and distant metastasis." (PMID 34699320, 2021). "IL-4 induced STAT6 signaling in promoting cell proliferation/growth and cell apoptosis resistance and induced epithelial-mesenchymal transition (EMT) in colorectal cancer cells via E2F1/SP3/STAT6 axis." (PMID 33506057, 2021). "For example, NFYB was reported to induce the high expression of E2F1 in colorectal cancer and mediate oxaliplatin resistance." (PMID 34933446, 2021). "miR-149 is a proapoptotic miRNA that affects the expression of the Akt1 and E2F1 gene, which has been shown to promote cell growth and cell cycle progression in IBD-associated colorectal cancer." (PMID 34659590, 2021). "Initially, we profiled the expression of FOXM1 and TYMS in colorectal cancer cell lines, and also measured the expression of E2F1 as it is known to regulate TYMS and FOXM1 expression, independently." (PMID 30728402, 2019). "The transcription factor E2F1 has been identified to be a oncogenic element in bladder cancer and colorectal cancer." (PMID 30482236, 2018). "For instance, E2F1 is suggested to be a probable target of cancer reversion due to its function to decrease the recurrence of colorectal cancer and arrest the cell cycle." (PMID 28381275, 2017). "Previous reports have revealed that down-regulation of miR-34a expression can promote colorectal cancer (CRC) cell growth by targeting cell cycle-related transcriptional factor E2F1." (PMID 28293146, 2017). "The E2F1 transcription factor is a key downstream target of pRB, and a potent and specific inhibitor of Wnt/β-catenin signaling in colorectal cancer cells." (PMID 27363012, 2016). "In support of this conclusion, it was recently reported that E2F1 plays a tumor suppressor role in colorectal cancer by activating CTNNBIP1 and inhibiting β-catenin activity." (PMID 23554908, 2013).
colorectal cancer (continued). "Considering all the previous evidence, we can only infer that the proteins pRB and E2F1 are acting with opposing roles in cervical cancer, as compared to colorectal cancer." (PMID 21696634, 2011). "Similarly, E2F-1 is a primary upstream regulator of cyclin A which is activated in colorectal cancer cells and its upregulation is found to be related with aggressive and malignant behavior of colorectal cancers." (PMID 37090250, 2023). "MiR-342-3p could repress colorectal cancer chemoresistance, and could act synergistically with miR-205-5p to reduce tumor chemoresistance by inhibiting E2F1." (PMID 34407841, 2021). "In addition, the role of E2F1 in various types of cancer, such as renal carcinoma, colorectal cancer, bladder cancer, and ovarian cancer, has been investigated." (PMID 34564711, 2021). "YY1 contributes to colorectal cancer development by the miR-526b-3p/E2F1 signaling." (PMID 35004266, 2021). "Researchers revealed that circCAMSAP1 might function as the sponge of miR-328-5p to regulate the expression of transcription factor E2F1, thereby promoting colorectal cancer (CRC) progression." (PMID 34262589, 2021). "Importantly, we found that activation of ICAT by E2F1 is required to inhibit β-catenin activity in colorectal cancers." (PMID 32326181, 2020). "Although E2F1 has pleiotropic roles in tumorigenesis, several lines of evidence have revealed that E2F1 promotes cell migration and aggressiveness in prostate and colorectal cancer cells." (PMID 31936744, 2020). "In colorectal cancer, researchers found that miR-362 may be involved in the regulation of the tumor cell cycle by affecting the expression of E2F1, USF2, and PTPN1." (PMID 32582765, 2020). "miR-361-3p downregulation may promote lymph node metastasis of T1-stage colorectal cancer via the upregulation of E2F1 or RAP2B expression." (PMID 30344797, 2018). "Moreover, our recent study reveals that XIAP directly binds to E2F1 via N-terminal BIR domains and enhances E2F1 transcriptional activity, which subsequently promotes colorectal cancer cell growth." (PMID 28057023, 2017). "Additional studies are indeed needed to evaluate the relationship between miR-17 and E2F1 in colorectal cancer and will require careful examination of their respective expression in sufficient morphologically characteristic regions present in such unique samples." (PMID 26465597, 2015). "RNAi-mediated reduction of E2F1 reduced expression of DSCC1 in colorectal cancer cells." (PMID 24465681, 2014). "However, we had to consider that all the published works that point to E2F1 as an inhibitor of c-Myc have been performed in colorectal cancer." (PMID 21696634, 2011). "Transcription factor E2F1 could promote RRM2 expression in colorectal cancer cell lines." (PMID 29651323, 2018). "NFYB-mediated upregulation of E2F1 enhances CHK1 signaling, contributing to chemotherapy resistance in colorectal cancer." (PMID 41424847, 2026). "Among them, three TF genes, E2F1, E2F3, and BRCA1, were validated as differentially expressed in databases of psoriasis and colorectal cancer, confirming their designation as hub TFs." (PMID 39045407, 2024). "In colorectal cancer, CDK8 phosphorylates E2F1 at the S375 site depending on its kinase activity rather than transcriptional activity, thus downregulating E2F1 transcriptional activity without affecting its protein stability." (PMID 38606172, 2024). "IRS4 is overexpressed in colorectal cancer, and when overexpressed in RKO cells, it induces the expression of cyclin D1, Cyclin E, E2F1, and pRB Ser 705 and pRB Ser809/811 genes." (PMID 37686244, 2023). "For example, in colorectal cancer, CDCA3 can mediate p21-dependent proliferation by regulating E2F1 expression or promote cell proliferation by activating the NF-KappaB /cyclin D1 signaling pathway." (PMID 34430085, 2021).
colorectal cancer (continued). "Since TS transcription has been shown to be regulated, at least in part, by E2F1, we then determined the expression level of E2F1 in HQGGT-treated colorectal cancer cells." (PMID 29458395, 2018). "E2F1 promoted miR-34c transcription which reduced its target stem cell factor (SCF) and inhibited colorectal cancer (CRC) cell proliferation." (PMID 26704889, 2015). "For head and neck, stomach, and colorectal cancer cases, co-high expression of E2F1 and MET did not significantly impact survival." (PMID 38957115, 2024). "Consistently, our recent study demonstrated that compared with E2F1 and E2F3, E2F2 might specifically play a pivotal role in colorectal cancer and serve as a specific therapeutic target." (PMID 35844795, 2022). "We have shown that E2 promoter binding factor 1 (E2F1) suppresses Wnt/β-catenin activity through transactivation of β-catenin interacting protein 1 (CTNNBIP1), also known as inhibitor of β-catenin and TCF4 (ICAT) in human colorectal cancers." (PMID 32326181, 2020). "Additionally, KDM5D inhibited tumor growth in colorectal cancer by demethylating E2F1 and suppressing FKBP4 transcription, thereby suggesting that it could possibly serve in the management of colorectal cancer in males." (PMID 37218871, 2023). "The non-SMC condensin II complex subunit D3 elevates E2F1 levels and enhances its recruitment to the promoter regions of PDK1 and PDK3, inhibiting pyruvate dehydrogenase activity and the tricarboxylic acid cycle in colorectal cancer." (PMID 41158756, 2026).
ovarian carcinoma (65 papers, 2010 to 2025). A malignant neoplasm originating from the surface ovarian epithelium. "We found that knockdown of E2F1 substantially suppressed the proliferation and metastasis of ovarian cancer cells, whereas re-expression of E2F1 in NSUN2-deficient cells mitigated the suppressive effect of NSUN2 knockdown on cell proliferation and metastasis." (PMID 38424195, 2024). "E2F1 has been implicated in the malignancy of several cancers; thus, we sought to characterize its role in ovarian cancer." (PMID 38424195, 2024). "The links between NSUN2-mediated RNA modification and transcriptional regulation by E2F1 prove the complexity of regulatory network underlying the malignancy of ovarian cancer." (PMID 38424195, 2024). "To further validate the implication of E2F1 in NSUN2-mediated ovarian cancer progression, we performed rescue assays in NSUN2-deficient ovarian cancer cells." (PMID 38424195, 2024). "E2F1 is well-known as a good prognostic indicator in ovarian carcinoma and its overexpression has been associated with unfavourable disease-free and overall survival." (PMID 37935712, 2023). "As far as we know, the present study is the first to investigate E2F1 polymorphisms with ovarian cancer risk." (PMID 35833075, 2022). "So far, the studies which explore the relationship between the E2F1 polymorphisms and ovarian cancer susceptibility are rare." (PMID 35833075, 2022). "MiR-424-5p inhibits CCNE1 expression (encoding cyclin E1) in ovarian cancer, and inhibits cell cycle by suppressing the E2F transcription factor 1 (E2F1)-RB transcriptional corepressor (PRb) pathway, which promotes apoptosis." (PMID 32960785, 2020). "t10,c12 CLA by inhibiting the expression of E2F1 is causing cell cycle arrest in the ovarian cancer cells." (PMID 29324748, 2018). "To explore the underlying molecular mechanism of the oncogenic effects of E2F1 on ovarian carcinoma, we focused on microRNAs (miRNAs)." (PMID 28146423, 2017). "We compared E2F1 expression levels in 59 cases of type I tumors and 17 normal ovarian tissues, and E2F1 expression was significantly elevated in the ovarian carcinoma tissues and was positively associated with FIGO stage I–II and III–IV disease." (PMID 28146423, 2017). "E2F1 factor, which is a transcription activator promoting the cell cycle, is overexpressed in epithelial ovarian cancers (EOC) and is associated with higher stage and tumour grade." (PMID 27480179, 2016). "In women with ovarian cancer, overexpression of E2F1 has been associated with decreased disease-free survival and decreased overall survival." (PMID 23637916, 2013). "It was found that interferon-gamma treatment for ovarian cancer caused a reduction of the proliferation-promoting TFs E2F1 and E2F2, at the same time it also increased the inhibiting TFs E2F4 and E2F5." (PMID 20181230, 2010). "We found that E2F1 deficiency dramatically impeded ovarian cancer cell growth." (PMID 38424195, 2024). "The CT genotype of E2F1 gene rs3213172 polymorphism is associated with an increased risk of ovarian cancer, and E2F1 gene rs3213172 polymorphism may be a novel marker for the risk prediction of ovarian cancer." (PMID 35833075, 2022). "The present study is aimed at exploring whether rs3213172, rs3213173, and rs3213176 polymorphisms of the E2F1 gene confer risk for ovarian cancer." (PMID 35833075, 2022). "The present study is to explore whether E2F1 gene polymorphisms confer risk for ovarian cancer." (PMID 35833075, 2022). "Downregulated genes in G1 condition were mainly associated with ovarian cancer tumors and xenografts down (dn), ELAVL1 targets up, liver cancer ciprofibrate up, liver cancer E2F1 up, liver cancer ACOX1 up, and SATB1 targets dn." (PMID 41479593, 2025). "A subcutaneous tumorigenesis model and peritoneal metastasis model were also used to investigate the oncogenic role of E2F1 in ovarian cancer in vivo." (PMID 38424195, 2024).
ovarian carcinoma (continued). "To confirm this, we further performed E2F1 ChIP assays in ovarian cancer cells following NSUN2 knockdown." (PMID 38424195, 2024). "Toward this end, we performed E2F1 ChIP-seq in ovarian cancer cells and identified 1804 binding sites within 1733 genes." (PMID 38424195, 2024). "The subcutaneous tumorigenesis assay revealed that E2F1 knockdown reduced the volume and weight of tumors formed from ovarian cancer cells, which phenocopied the effect of NSUN2 deficiency." (PMID 38424195, 2024). "In vitro Transwell assays also revealed that E2F1 inhibition significantly diminished the migration and invasion abilities of ovarian cancer cells." (PMID 38424195, 2024). "E2F1 affects NSUN2 transcription by interacting with the NSUN2 promoter, thus suggesting that NSUN2 and E2F1 form a positive feedback loop in ovarian cancer." (PMID 38424195, 2024). "In this study, we revealed that the RNA methyltransferase NSUN2 facilitates mRNA m5C modification and forms a positive feedback regulatory loop with the transcription factor E2F1 in ovarian cancer." (PMID 38424195, 2024). "m5C modification of E2F1 mRNA directs its regulation of target gene expression, which is implicated in the NSUN2-mediated tumor-promoting effect on ovarian cancer." (PMID 38424195, 2024). "Western blot analysis revealed that YBX1 knockdown decreased the protein expression of E2F1 in ovarian cancer cells, and half-life assays showed that YBX1 increased the stability of E2F1 mRNA." (PMID 38424195, 2024). "BTYNB inhibited the malignant process of ovarian cancer by weakening the stability of IGF2BP1 on E2F1 mRNA, thus limiting the protein translation of E2F1." (PMID 38343637, 2024). "The colony formation assay showed that the colony numbers in all three ovarian cancer cell line groups were substantially decreased upon E2F1 knockdown." (PMID 38424195, 2024). "Intriguingly, we found that NSUN2 protein expression decreased following E2F1 knockdown when we investigated the function of E2F1 in ovarian cancer cells." (PMID 38424195, 2024). "Accordingly, E2F1 knockdown attenuated the metastasis of ovarian cancer cells to the peritoneal cavity." (PMID 38424195, 2024). "Using the same dataset, we also observed high levels of PD‐L1, PD‐1, FOXP3, and E2F1 in the ovarian cancer samples that expressed high levels of SPHK1 compared to samples that expressed low levels." (PMID 35289120, 2022). "In ovarian cancer, low expression of E2F1 was reported to be correlated with favorable disease-free survival (DFS) and OS." (PMID 34966670, 2021). "In summary, these data indicated that DDX23 was a direct transcriptional target of E2F1 in ovarian cancer cells." (PMID 34966670, 2021). "The differential expression analysis of the 5 TFs were performed using TCGA-GTEx data, and the results showed that the expression of E2F1 in ovarian cancer increased most significantly compared to the other 4 TFs." (PMID 34966670, 2021). "In Bonome's dataset, E2F1 was overexpressed in ovarian carcinoma with a fold change of 1.644 and p–value of 2.60E-07." (PMID 30967995, 2019). "Deregulated E2F1 expressions have been found in many types of cancers, including lung, esophageal, gastric, colon, pancreatic, breast and ovarian cancer, etc." (PMID 31801947, 2019). "Both genetic and pharmacological inhibition of E2F1/4 family members enhance DIRAS3-mediated autophagy in ovarian cancer cells." (PMID 31052266, 2019). "In contrast, our studies in multiple ovarian cancer cell lines found that E2F1 represses BRCA1 expression, and that this repression requires the DNA methyltransferase DNMT1 and is correlated with CpG hypermethylation of the BRCA1 promoter." (PMID 31604914, 2019). "Knockdown of E2F1 in A2780 and SKOv3 ovarian cancer cells induced autophagy measured by LC3 conversion on western blot analysis and puncta formation by immunofluorescence staining." (PMID 31052266, 2019).